CASP1 (caspase 1)
Diseases named in the same sentence as CASP1 in open-access papers (continued):
Sharing a sentence is not in itself a finding about the gene and the disease.
prostate carcinoma (continued). "Bcl-2 overexpression plays a role in the development of androgen-independent prostate cancer cells, conferring resistance to apoptosis by an antagonistic effect in caspase 1 activation, providing resistance to radio and chemotherapies." (PMID 24629090, 2014). "Caspase 1 is an important regulator of epithelial cell apoptosis and its downregulation has been reported in breast, gastric, colon and prostate cancers." (PMID 17164758, 2007). "Furthermore, compound 33 combines SMAC mimetic and anti-androgenic elements through a polyethlenic linker and induces pyroptosis in prostate cancer cells via caspase-1 activation." (PMID 39316325, 2025). "It induces pyroptosis in prostate cancer cells through the activation of caspase-1." (PMID 39316325, 2025). "However, it is inconsistent with the results of the expression of CASP1 in prostate cancer and ovarian cancer." (PMID 33999861, 2021). "CASP1 decreased significantly in prostate cancer and ovarian cancer, indicating that down-regulation of CASP1 may play an important role in the carcinogenesis and progression of tumors." (PMID 33999861, 2021). "Furthermore, CASP1 is frequently downregulated in prostate cancer and its genetic restoration reduces the tumorigenic potential via apoptosis." (PMID 28388569, 2017). "To determine whether CYP1B1 expression is correlated with CASP1 level, we first examined the level of CASP1 in prostate cancer tissue samples." (PMID 28388569, 2017). "On the other hand, since anti-androgen treatment led to anticancer effects in early stage prostate cancer and suppression of caspase-1 at the same time, it is possible that caspase-1 plays a pro-cancer role in the secretion of proinflammatory cytokines to facilitate cancer aggressive invasion." (PMID 28360909, 2017). "Caspase-1 is also downregulated in prostate cancer which is speculated to prolong the cancerous cell life span." (PMID 28360909, 2017). "In addition, a cytochrome P450 1B1 inhibitor could suppresses the tumorigenicity of prostate cancer via the upregulation of caspase-1." (PMID 31941010, 2020). "Signature tumor suppressor genes of prostate cancer such as Rb, PTEN, Caspase 1, and Tob-1 were underexpressed in LPB-Tag tumors but were overexpressed in the prostates of LPB-TagCTRKO genotype." (PMID 32180899, 2020). "Of note, hypoxia increased the basal activation of caspase 1 in human normal PrECs, BPH-1 cells line, prostate cancer PC-3 and THP-1 myeloid cell lines." (PMID 27058421, 2016). "In prostate cancer, TGF-β-mediated apoptosis involves: (i) caspase 1 activation 80; (ii) up-regulation of pro-apoptotic factors (e.g. Bax, p27KIP1); and/or (iii) down-regulation of antiapoptotic factors (e.g. Bcl-2 and Bcl-xl) 51,81." (PMID 24629090, 2014). "Carvedilol (CVL), a β-adrenergic receptor antagonist, promotes NF-κB nuclear translocation through the NLRP3-caspase-1-ASC inflammasome, inducing pyroptosis in prostate cancer (PCa) cells and establishing a foundation for the application of β-adrenergic antagonists in PCa treatment." (PMID 40718836, 2025). "This suggests that the expression patterns of Caspase-1 and the AIM2 inflammasome might have prognostic significance for disease progression in prostate cancer." (PMID 36702978, 2023). "We found that the advanced stage prostate cancer PC3 cells, exhibit comparable NLRP3 protein expression level but higher pro-IL-1β and active P-20 fragment of caspase-1, paralleled by doubled IL-1β secretion level after 48 h of culture compared to the androgen-sensitive LNCaP cells." (PMID 34070682, 2021). "The dominant expression of inflammasome complex proteins (ASC and pro-caspase-1) in aggressive prostate cancer cell lines implicate the role of NLRP12 inflammasome provoking inflammatory events via regulating IL-1β and IL-18 in the development and progression of prostate cancer." (PMID 28663562, 2017).
rheumatoid arthritis (26 papers, 2014 to 2026). A chronic, systemic autoimmune disorder characterized by inflammation in the synovial membranes and articular surfaces. "IL-1β generation is mainly mediated by the NLRP3 inflammasome, and deletion of Nlrp3, caspase-1 and the IL-1 receptor markedly protects against rheumatoid-arthritis-associated inflammation." (PMID 29743895, 2018). "Drugs inhibiting IL-1, P2X7R, and caspase-1 have been developed, although to date only IL-1 inhibitors have been successful in clinical studies of rheumatoid arthritis (RA) and cryopyrin-associated periodic syndrome (CAPS)." (PMID 24450291, 2014). "Caspase-1 and caspase-3 play pivotal roles in the pathogenesis of chronic inflammatory diseases such as rheumatoid arthritis (RA) and psoriasis." (PMID 40555741, 2025). "Of the compounds targeting caspase-1, VX-740 showed good anti-inflammatory performance in phase 1 and phase 2 trials for rheumatoid arthritis but the trials were discontinued due to drug-related hepatotoxicity." (PMID 39353903, 2024). "Our understanding of the AIM2 inflammasome’s role in pathogenesis has been furthered by observations of its upregulated expression, alongside that of ASC and Caspase-1, in PBMCs and neutrophils of rheumatoid arthritis patients." (PMID 39100670, 2024). "The finding also indicates that A20 deficiency in macrophages significantly enhances NLRP3 inflammasome-mediated caspase-1 activation and IL-1 β secretion, which contributes to the pathology of rheumatoid arthritis in vivo." (PMID 35794098, 2022). "In patients with rheumatoid arthritis, active caspase 1 cleaved IL-1β precursors and IL-18 precursors to IL-1β and IL-18 to induce inflammation, respectively." (PMID 31367484, 2019). "Deficiency of NLRP3 or caspase-1/-11 in A20 knockout mice protected against the inflammatory symptoms of rheumatoid arthritis, which showed that A20 negatively regulated NLRP3 inflammasome activity in rheumatoid arthritis." (PMID 36387275, 2022). "However, another study found that caspase 1 expression was decreased in patients with rheumatoid arthritis, but the activity of caspase 1 was significantly increased, which only promotes the production of IL-18, not IL-1β." (PMID 31367484, 2019). "For example, patients with Sjogren’s syndrome, rheumatoid arthritis, and systemic lupus erythematouses, dermatomyositis and polymyositis have the feature of caspase 1-mediated release of inflammatory factors." (PMID 31367484, 2019). "Our study complemented previous studies that showed that caspase 1 level in CTD inclduing rheumatoid arthritis, SLE, Sjogren’s syndrome, dermatomyositis and so on, whether in tissues or in plasma, increased significantly." (PMID 31367484, 2019). "In addition, Pentaxin 3, which is upregulated in the plasma of patients with rheumatoid arthritis, can act synergistically with the ligand C1q to activate NLRP3 inflammasome, causing caspase-1-mediated pyroptosis and inflammatory cytokines, the degree of which was consistent with disease activity." (PMID 37386410, 2023). "In addition, higher levels of NLRP3 and caspase-1 were observed in patients with rheumatoid arthritis than in patients with degenerative arthritis, and it was found that the administration of selective NLRP3 inhibitors reduced redness and cartilage degradation." (PMID 36619197, 2022). "Caspase-1 expression in rheumatoid arthritis (RA) synovial fibroblasts treated with TNF was assessed by qRT-PCR and Western blot." (PMID 24762050, 2014). "In rheumatoid arthritis (RA), patients exhibited reduced levels of AIM2 in their sera compared to healthy individuals, whereas levels of ASC, Caspase-1, and IL-1β are elevated." (PMID 39600708, 2024). "We demonstrated that methotrexate play an inhibitory effect on rheumatoid arthritis swelling and inflammation by downregulating NF-κB and NLRP3/Caspase-1 pathways and potentially affecting the activity of caspase-1." (PMID 30249062, 2018).
rheumatoid arthritis (continued). "VX-765 is structurally similar to VX-740, acting by covalent modification of the catalytic cysteine residues in the caspase-1 active site, which has been tested in phase II trials for psoriasis and epilepsy, but not yet in rheumatoid arthritis." (PMID 35833125, 2022). "Interestingly, A20 deficiency in macrophages significantly enhanced NLRP3 inflammasome-mediated caspase-1 activation, pyroptosis, and IL-1β secretion, and negative regulation of the NLRP3 inflammasome by A20 protected against rheumatoid arthritis." (PMID 35794098, 2022).
Hepatic steatosis (25 papers, 2013 to 2025). Steatosis is a term used to denote lipid accumulation within hepatocytes. "Another study using NLRP3−/−, ASC−/−, and caspase-1−/− mice also found that hepatic steatosis and inflammation in NASH were indeed associated with activation of the NLRP3 inflammasome." (PMID 36016562, 2022). "Caspase-1-deficient mice are protected from high fat-induced hepatic steatosis, inflammation, and early fibrogenesis, suggesting that pyroptosis-related caspase-1/inflammasomes promote NASH progression." (PMID 34859106, 2021). "In a high fat diet-induced NASH model, deficient Casp-1 animals showed improvement in hepatic steatosis, inflammation and fibrogenesis." (PMID 32431709, 2020). "For example, mice deficient in caspase-1 exhibited less high fat diet-induced hepatic steatosis, inflammation, and early fibrogenesis." (PMID 28729463, 2017). "For example, one report shows that caspase-1 deficiency mice were protected from high fat-induced hepatic steatosis, inflammation and early fibrogenesis." (PMID 27942420, 2016). "Specifically, mice deficient in caspase-1 are protected from high fat-induced hepatic steatosis, inflammation and early fibrogenesis." (PMID 23409132, 2013). "In agreement with the decreased hepatic inflammation observed in clodronate-treated mice, caspase-1-deficient mice (that lack IL-1β expression) exhibit attenuated diet-induced hepatic steatosis and significant decreases in hepatic lipogenic gene expression compared with wild type control mice." (PMID 25216251, 2014). "Taxifolin also alleviates inflammatory responses induced by caspase-1 activation in steatotic hepatocytes, inhibiting lipid accumulation and caspase-1-associated pyroptosis, and demonstrates therapeutic effects on alcohol- and HFD-induced fatty liver." (PMID 39858534, 2025). "Hepatic steatosis and injury of liver function increased in Casp1(−/−) mice on HF diet compared with their wild-type counterparts." (PMID 30429827, 2018). "In this study, our results demonstrate that ER stress-induced liver steatosis was significantly attenuated in caspase-1 KO mice." (PMID 27942420, 2016). "Our results suggest that ER stress-induced hepatic steatosis and inflammation are regulated by caspase-1 activity." (PMID 27942420, 2016). "For example, the high fat diet increased hepatic steatosis and expression of lipogenesis related genes in wild-type mice, but Casp1-/- mice were protected from these diet-induced phenotypes." (PMID 23409132, 2013). "Thus, the development of fatty liver disease in mice deficient in NLRP3 (Nlrp3−/−) or its essential components (Asc−/− and Casp1−/− mice) can be avoided if they consume a high fat or nutrient-deficient diet." (PMID 32194416, 2020). "We found that ER stress-induced liver steatosis was significantly attenuated in caspase-1 KO mice." (PMID 27942420, 2016). "Thus, lower expression of hepatic TNFα and MCP-1 in Casp1-/- mice compared to wild-type mice on the high fat diet likely contributed to a decrease in high fat diet-induced hepatic steatosis." (PMID 23409132, 2013). "In addition to alcohol, drugs and viruses, NLRP3/Caspase 1 may be activated through saturated fatty acids, and Caspase 1 knock out prevents hepatic steatosis in animal models." (PMID 33807722, 2021). "If Casp1-/- mice on high fat diet were protected from hepatic steatosis due to increased VLDL secretion, we would expect to observe an increase in expression of genes associated with the formation and/or secretion of VLDL in caspase-1 deficient mice compared to wild type mice." (PMID 23409132, 2013). "A previous study showed that CBD alleviated hepatic steatosis and oxidative stress and significantly decreased the expression of NF-κB, NLRP3, ASC, procaspase-1, caspase-1 p20, GSDMD, and cleaved GSDMD both in vivo and in vitro." (PMID 36016562, 2022).
Hepatic steatosis (continued). "To investigate whether the preventive effect of SFN on hepatic steatosis was associated with the suppression of the NLRP3 inflammasome in vivo, we determined the expression levels of NLRP3 inflammasome components (including NLRP3, ASC, and caspase-1) in the livers." (PMID 27075683, 2016). "Here, caspase-1/11-/- mice fed an MCD diet for 4 weeks had higher levels of ALT and AST, as well as more microvesicular and macrovesicular hepatic steatosis, and more hepatic inflammation than their C57Bl6 wild-type controls fed the same diet." (PMID 24312444, 2013). "Furthermore, it inhibits ferroptosis through the SIRT1/Nrf2 pathway, improving fatty liver disease, and blocks NLRP3-Caspase-1-GSDMD-mediated pyroptosis in H9C2 and RAW264.7 cells." (PMID 40391374, 2025). "Casp-1 and ASC, as well as inflammasome complexes, have been found as master regulators of IL-1β activation or signaling, which is required for the development of liver steatosis, inflammation, and damage." (PMID 33265944, 2020). "Hepatic steatosis and TG levels were increased in wild-type mice on high fat diet, but were attenuated in the absence of caspase-1." (PMID 23409132, 2013). "The Casp1 KO mice also developed fibrosing NASH and compared to WT mice, they had similar body weight, liver weight/body weight ratio, average food consumption, plasma levels of ALT, AST and ALP, and hepatic steatosis, inflammation and fibrosis measured by Sirius red." (PMID 36641116, 2023). "In line with our hypothesis, when these mice were fed an HFC diet, deletion of caspase-1/11 in KCs resulted in less hepatic inflammation compared to controls, which was independent of the development of hepatic steatosis." (PMID 24312444, 2013). "High-fat diet (HFD)-fed caspase-1-/- mice showed improved liver steatosis compared to wild-type mice, though ALT levels did not correspondingly improve, indicating caspase-1 knockout did not alleviate hepatocyte injury." (PMID 38380334, 2024).
periodontitis (25 papers, 2016 to 2026). An acute or chronic inflammatory process that affects the tissues that surround and support the teeth. "Periodontitis is associated with caspase and proinflammatory mediators, such as caspase-1 and tumor necrosis factor-alpha (TNF-α)." (PMID 36794778, 2023). "One study found that caspase-1 deficiency suppressed the secretion of inflammation factors from macrophages and alleviated bone resorption in periodontal tissue during periodontitis." (PMID 36093182, 2022). "We find from the database DisGeNET that 4 high-ranking target proteins, Interleukin-1 beta (3rd), Caspase-1 (3rd), Caspase-3 (3rd) and Matrix metalloproteinase-9 (3rd), are associated with the top disease Periodontitis (1st)." (PMID 35249529, 2022). "This study investigates the role of NLRP3 inflammasome and its main effector Caspase-1 in inflammation and alveolar bone resorption associated with periodontitis." (PMID 32385413, 2020). "Correspondingly, compared with wild-type controls, NLRP3- or caspase-1–deficient mice exhibit significantly less alveolar bone loss in ligature-induced periodontitis models, underscoring the crucial role of inflammasome signaling in periodontal bone resorption." (PMID 41596738, 2026). "Clinical studies have consistently demonstrated elevated levels of NLRP3, caspase-1, IL-1β, and IL-18 in the gingival tissues and gingival crevicular fluid of patients with periodontitis, correlating with attachment loss, probing depth, and bleeding on probing." (PMID 41596738, 2026). "In addition, other proinflammatory and anti-inflammatory cytokines need to be investigated for a possible association with caspase-1 and periodontitis." (PMID 36794778, 2023). "We speculate that activation of other Caspase-1 activating inflammasomes may compensate the inactivation of Nlrp3 in Nlrp3-KO mice, which may account for the lack of influence on bone resorption associated with experimental periodontitis in these mice." (PMID 32385413, 2020). "In patients with poorly controlled type 2 diabetes, those with chronic periodontitis displayed higher caspase-1 mRNA levels and elevated protein levels of NLRP3, ASC, and IL-1β compared with periodontitis patients who were not diabetic." (PMID 41440367, 2025). "Clinical and experimental evidence strongly support the involvement of caspase-1 and caspase-4 in the pathogenesis of periodontitis." (PMID 40137780, 2025). "In a more recent study, a decrease in AIM2 for chronic periodontitis patients was reported, with an increasing trend in the expression of caspase-1 between chronic periodontitis, aggressive periodontitis groups, and healthy subjects." (PMID 41440367, 2025). "The salivary biomarkers caspase-1 and TNF-α showed high diagnostic accuracy in distinguishing periodontal health from periodontitis." (PMID 36794778, 2023). "TNF-α and caspase-1 salivary levels were higher in periodontitis patients than in healthy controls and were positively correlated with all clinical parameters." (PMID 36794778, 2023). "Among all the pyroptosis-related inflammasomes and caspases, NLRP3 and caspase-1 are the most comprehensively characterized members in periodontitis." (PMID 36093182, 2022). "The immunological analysis performed in our study generated comparable outputs on the average values of CASP1 within the GCF samples of periodontitis patients, which were significantly higher than those of healthy controls." (PMID 34840527, 2021). "Human gingiva samples were immunohistochemically characterized for the expression of NLRP3, 8OHdG, cleaved-caspase-1, and IL-1β in periodontitis specimens, compared with that in normal gingival tissues." (PMID 31685946, 2020). "The NLRP3 inflammasome and its effector molecules (IL-1β and caspase-1) play roles in the development of periodontitis." (PMID 31341421, 2019). "In support of caspase-1-mediated cell death, pyroptosis, we found co-expressions of cleaved-caspase-1 and Tunel in the periodontitis tissues." (PMID 29184853, 2017).